YY1 (YY1 transcription factor)
Diseases named in the same sentence as YY1 in open-access papers (continued):
Sharing a sentence is not in itself a finding about the gene and the disease.
tumor (continued). "The key transcription factors driven by H3K18la, YBX1 and YY1, further enhance the resistance of Bca patients to cisplatin, which is unfavorable for tumor treatment." (PMID 40704062, 2025). "A particularly interesting finding in our study was strong nuclear YY1 expression in tumor-infiltrating immune cells." (PMID 41009346, 2025). "For a more profound comprehension of YY1's role in immunotherapy outcomes, we engaged bioinformatics analysis to explore the link between YY1 expression and immune cell infiltration within the tumor microenvironment." (PMID 41322030, 2025). "This transition is driven by molecular adaptations, including the overexpression of transcription factor Yin Yang 1 (YY1), which promotes tumor plasticity and survival under ADT pressure." (PMID 41029459, 2025). "Mass‐spectrometric profiling of tumor tissues from anti‐PD‐1‐responsive versus non‐responsive HCC patients identified the transcription factor YY1 as a key regulator." (PMID 41322030, 2025). "In CRC, USP7 also plays a key role in regulating YY1 protein levels, which promote tumor development." (PMID 40568598, 2025). "Then, we explored the clinical relevance of YY1 in BC, comparing nuclear protein expression in matched tumor and normal BC samples from our cohort." (PMID 41009346, 2025). "This activity promotes tumor survival under metabolic and therapeutic stress, positioning YY1 as a potential target for inducing ferroptosis in the treatment of refractory tumors." (PMID 41029459, 2025). "While YY1 can promote pathological responses such as lipid accumulation and tumor-supportive polarization, it also sustains immune homeostasis and cell survival under stress." (PMID 41459495, 2025). "IHC analysis revealed markedly lower YY1 nuclear staining in normal breast epithelial cells than in tumor cells, where strong nuclear expression was consistently observed." (PMID 41009346, 2025). "YY1 reshapes the tumor immune microenvironment, including DNA methylation patterns, histone post-translational modifications, non-coding RNA networks, and core oncogenic signaling pathways, thereby promoting immune escape." (PMID 40867514, 2025). "Regarding drug resistance mechanisms, YY1 not only mediates immune escape through immune checkpoints but also coordinately regulates tumor metabolism." (PMID 40867514, 2025). "YY1 can help tumor cells escape immune response by regulating LAG‐3 expression in CD8+ T cells within tumors." (PMID 40088083, 2025). "At the level of signaling pathways, YY1 exerts its oncogenic influence by activating tumor promoting pathways while simultaneously inhibiting tumor suppressive pathways." (PMID 41327312, 2025). "Silencing YY1 via siRNA not only suppresses tumor proliferation and metastasis in vitro but also delays subcutaneous tumor growth in vivo, positioning it as a compelling therapeutic target." (PMID 41029459, 2025). "YY1 is involved in tumor resistance to immune checkpoint inhibitors (ICIs) immunotherapy, achieved through the positive regulation of PD-1 and LAG-3." (PMID 39796650, 2024). "Of importance, the expression of PD-L1 on tumor cells has been demonstrated to be regulated by the overexpression of the transcription factor (TF) Yin Yang 1 (YY1)." (PMID 38539569, 2024). "SRF expression has been proved to drive the hepatocarcinogenesis 35, tumor aggressiveness 36, and sorafenib resistance 37 and YY1 induced cell proliferation 38 and tumor angiogenesis 39 in HCC." (PMID 39247819, 2024). "Ying Yang (YY1) serves as a pivotal transcription factor in tumor development, with its overexpression strongly correlating with various malignant processes such as cancer metastasis, EMT transition, drug resistance, and unfavorable prognoses." (PMID 38786085, 2024). "Such insights hold the potential to guide the development of novel therapeutic strategies targeting YY1 for effective tumor therapy." (PMID 38347631, 2024).
tumor (continued). "YY1 promotes tumor angiogenesis by stabilizing the hypoxia-inducible factor-1α (HIF-1α) and activating angiogenic factors like vascular endothelial growth factor (VEGF) and transforming growth factor alpha (TGF-α)." (PMID 38893192, 2024). "YY1 plays a substantial role in the progression of multiple tumor types, albeit with varying mechanisms through which it promotes tumor growth." (PMID 38347631, 2024). "As a transcription factor or inhibitor, YY1 has two roles in cancer: tumor promotion or tumor suppression." (PMID 38351178, 2024). "Although YY1 plays important roles in cancer progression, the mechanisms by which YY1 promotes tumor growth are complex and not well understood." (PMID 38351178, 2024). "To confirm the synergistic effect of KDM5C and YY1 on tumorigenicity and cancer cell proliferation, we analyzed the cell cycle progression and apoptosis rate of tumor cells in which KDM5C, YY1 or both had been depleted." (PMID 39433896, 2024). "EZH2 has also been shown to interact with YY1 in various pathways, including silencing tumor-suppressive miRNAs and other pro-tumorigenic properties." (PMID 38539569, 2024). "The overwhelming body of evidence suggests that YY1 predominantly functions to facilitate tumor development in various cancers." (PMID 38769122, 2024). "Inhibiting YY1 has shown significant promise in hindering tumor phenotypes and reversing resistance." (PMID 38893192, 2024). "YY1 has been reported to be overexpressed in many cancers, contributing to either tumor suppression or progression depending on the cancer type." (PMID 38893192, 2024). "YY1-siRNA in combination with a tumor-specific delivery system such as a peptide-decorated exosome is a possible mechanism of YY1 inhibition and requires further exploration." (PMID 38539569, 2024). "Here, we provide an overview of the interplay between tumor angiogenesis and immune modulation and review the function and mechanism of the YY1-HIF axis that regulates the vascular and immune tumor microenvironment." (PMID 38339244, 2024). "YY1 can promote tumor progression and survival by activating certain oncogenes such as c-Myc and cyclin D1, and surviving." (PMID 39796650, 2024). "In contrast, depleting YY1 in low KDM5C-expressing tumor cells completely eliminated chromatin-bound YY1 and promoted tumor regression." (PMID 39433896, 2024). "To verify the promotive effect of YY1 on tumor growth in vivo, we injected YY1-overexpressed GC cells and measured the tumor progression." (PMID 38347631, 2024). "Although YY1 was highly expressed in tumor lesions compared to adjacent normal tissues at baseline, a consistent reduction was observed in post-treatment versus pre-treatment samples." (PMID 39604408, 2024). "This inference seems plausible since YY1 was shown to have high mRNA expression in most different types of tumor tissues." (PMID 39796650, 2024). "The contrasting roles of YY1 as a tumor suppressor or tumor promoter likely rely on its interacting partners in a different tumor setting, which suppresses or promotes the expression of several genes and non-coding RNAs." (PMID 38351178, 2024). "By promoting GLUT3 transcriptional activities, YY1 enhances the Warburg effect and tumor cell proliferation." (PMID 38351178, 2024). "The transcription factor YY1 is overexpressed in most tumors and participates in regulating the resistance of tumor cells to cellular immunotherapy." (PMID 39796650, 2024). "Recent findings provide new insights into the development of targeted therapies designed to inhibit YY1 in tumor growth and resistance to chemotherapy and immunotherapy." (PMID 38893192, 2024).
tumor (continued). "It was shown in further preclinical studies that RNA interference was able to knock down YY1, and this promoted apoptosis, inhibited cell proliferation, and enhanced the effectiveness of chemotherapy in tumor cells for these trials." (PMID 39796650, 2024). "For example, YY1 knockdown completely abolishes the tumor-forming ability of the high tumorigenic bladder cancer cell line UMUC3." (PMID 39796650, 2024). "We have investigated an alternative approach to prevent the expression of PD-L1 on tumor cells, through targeting the oncogenic transcription factor Yin Yang 1 (YY1), a known factor overexpressed in many cancers." (PMID 38539569, 2024). "YY1 overexpression in anti-tumor CD8 T cells regulates immune evasion, in part through its transcriptional regulation of LAG-3." (PMID 39796650, 2024). "We observed that mIFN-α treatment partially reversed YY1-mediated tumor growth and drug resistance by increasing the expression of CD8 and CD27, markers of T cell activation, in GC tissues." (PMID 38347631, 2024). "We explored the significance of the relationship between YY1 expression and the tumor immune microenvironment via the Spearman’s correlation coefficients between YY1 and immune infiltration." (PMID 38347631, 2024). "The findings are consistent with the role of YY1 in promoting tumor development through the repression of tumor suppressor genes and activation of tumor-promoting genes, as YY1 performs bidirectional transcriptional regulation depending on the context." (PMID 38769122, 2024). "Another mechanism by which YY1 is involved is tumor resistance to ICI immunotherapy, achieved through the positive regulation of programmed death receptor-1 (PD-1)/and LAG3." (PMID 38339244, 2024). "Taken together, these results suggest that Silibinin represses GBM tumor growth by inhibiting the YY1/SLC1A5 pathway." (PMID 38410123, 2024). "Preclinical studies have effectively demonstrated the role of YY1 inhibition in the regulation of tumor growth, apoptosis, and cancer cell sensitization to chemotherapy." (PMID 38893192, 2024). "YY1 inhibits the activation of T cells and promotes immune tolerance in tumor cells by activating the expression of inhibitory receptors such as PD-1." (PMID 39796650, 2024). "In order to delve deeper into this phenomenon, we compiled a cohort comprising 30 CRC patients encompassing varying TB grades (with an equal distribution of 10 patients per grade) and evaluated the expression of YY1 within their tumor tissues." (PMID 38769122, 2024). "Further studies are important to develop selective YY1-targeting agents and test them for their anti-tumor efficacies in preclinical studies, followed by clinical studies." (PMID 39796650, 2024). "In contrast, exogenous YY1 expression attenuated erlotinib efficacy, as exemplified by larger tumor masses with gained weight." (PMID 39604408, 2024). "In preclinical studies, YY1 inhibition has shown efficacy in inhibiting tumor growth, promoting apoptosis, and sensitizing tumor cells to chemotherapy." (PMID 37444616, 2023). "Among these possible genes, YY1 was selected for that YY1 is an important regulator in tumor metastasis." (PMID 36195720, 2023). "In adenomatous polyposis coli (APC)‐derived tumor models, overexpressed YY1 activates Wnt signaling, thus resulting in augmented tumor growth." (PMID 36880159, 2023). "An abnormally high YY1 expression in tumor cells indicates that a stable factor of YY1 exists in tumor cells." (PMID 37408047, 2023). "Up-regulated LINC00958 promotes tumor cell proliferation and promotes tumor growth in mice through the LINC00958/miR-378a-3p/YY1 axis." (PMID 37901333, 2023).
tumor (continued). "Higher YY1 levels are also correlated with enhanced tumor phenotypes; however, this is largely dependent on the tumor context." (PMID 37686541, 2023). "In recent years, molecular diagnosis has become an important strategy for clinical tumor diagnosis and prognosis evaluation based on the expression specificity and clinical relevance of YY1 in different tumors." (PMID 37081988, 2023). "In summary, YY1 is another crucial transcription factor inducing NE differentiation in PCa that promotes tumour cell growth and metastasis in vivo and in vitro." (PMID 37771187, 2023). "Given that the effect of tumor immunotherapy can be regulated by YY1, we further proposed a drug-development strategy that combined the regulation of YY1 expression with ICIs." (PMID 37408047, 2023). "Simultaneously, YY1 inhibits the expression of E-cadherin, a protein crucial for cell–cell adhesion, further enabling tumor cell migration." (PMID 37444616, 2023). "In conclusion, research on the molecular mechanisms of the G6PD-mediated PPP is closely related to YY1-induced tumor cell proliferation and tumorigenesis." (PMID 37081988, 2023). "HCC is a well-known typical angiogenesis-dependent solid tumor with rich blood vessels, and YY1 is reported to be involved in regulating tumor malignancy in HCC." (PMID 37081988, 2023). "Based on the functions of YY1 in tumor angiogenesis, metabolism and tumor-related microenvironment reconstruction, targeting YY1 are expected to become an important molecular strategy for tumor therapy." (PMID 37081988, 2023). "The miR-7 is also involved in directly targeting YY1 through negative regulation and acts as a tumor suppressor as it stimulates apoptosis and cell-cycle control." (PMID 37686541, 2023). "Of the included 491 cases, nuclear YY1 expression in tumor cells was high in 138 cases (28.1%) and low in 353 cases (71.9%) based on IHC staining." (PMID 37444605, 2023). "One small molecule that has been investigated for its potential as a YY1 inhibitor is DETA-NONOate, which was reported in both in vitro and in vivo studies to inhibit the activities of YY1 and Bcl-xL, two proteins that can help tumor cells resist chemotherapy." (PMID 37444616, 2023). "One potential approach is the use of antibody–drug conjugates (ADCs) for the selective delivery of YY1 inhibitors into tumor cells, thus minimizing the off-target effects on normal cells." (PMID 37444616, 2023). "Conversely, ectopic YY1 expression can lead to enhanced tumor invasion activity, migration and tumor activity in gastric cancer, nontumorigenic human mammary MCF-10A cell lines and hepatocyte cells." (PMID 37686541, 2023). "In preclinical studies, inhibiting YY1 has shown promise in slowing tumor growth, promoting cell death, and increasing the effectiveness of chemotherapy." (PMID 37444616, 2023). "Intriguingly, many YY1‐repressed genes exhibit tumor suppressive potential while YY1 silencing is related to chemotherapy resistance." (PMID 36880159, 2023). "Yin-yang-1 (YY1), a transcription factor regulator, is aberrantly expressed in various cancers, where it regulates diverse processes ranging from tumor cell invasion and metastasis to cell survival and proliferation." (PMID 37408047, 2023). "Let7a targets Bcl-xL and acts as a tumor suppressor, so the siRNA YY1 blocks YY1 from suppressing Let7a and allows for chemosensitivity in tumor cells." (PMID 37686541, 2023). "Small molecule inhibitors that disrupt the interaction between YY1 and its DNA binding sites have shown promising results in preclinical studies by inhibiting tumor growth and metastasis in various types of cancer." (PMID 37444616, 2023). "Several recent reports suggest that YY1 mostly acts as an oncogene in most types of cancers but also acts as a tumor suppressor in some other types of cancer." (PMID 37081988, 2023).
tumor (continued). "YY1 is reported to be widely expressed in various tissues, acting either as an oncogene or as a tumor suppressor, thus playing a dual role in cancer development and progression in a cancer type-specific manner." (PMID 37894300, 2023). "Overall, YY1 has garnered extensive research interest for its role in gene regulation in tumor cells, exhibiting both activation and repression capabilities." (PMID 37444616, 2023). "In this review, we will explore the potential of YY1-targeted therapy as a novel approach for tumor treatment and provide an overview of the different strategies that have been explored in preclinical and clinical studies." (PMID 37444616, 2023). "Targeting YY1 in cancer cells for its inhibition or targeting its protective proteins will reverse resistance and allow for cancer cells to respond to therapies, tumor regression and the prolongation of survival." (PMID 37686541, 2023). "Herein, we reviewed the expression pattern of YY1 in tumors and summarized the function and mechanism of YY1 in regulating tumor angiogenesis, immune and metabolism." (PMID 37081988, 2023). "We thus explored the associations between YY1 (or PEBP1) expression and immune signatures, tumor immune cell infiltration, TMB, stemness, and microsatellite instability (MSI) in the TCGA database, using the R package “UCSCXenaShiny”." (PMID 37894300, 2023). "Due to YY1′s role as a regulator of many genes, it has been shown to have implications with tumor growth as a promoter or suppressor." (PMID 37686541, 2023). "With the increase of differentiation grade of CRC, the expression level of YY1 increases, indicating a potential tumor promotion role of YY1 in CRC." (PMID 36880159, 2023). "Overall, YY1 expression correlated significantly with most of TIMER’s immune signatures across most of the different tumor types, including T cell C8+, neutrophil, DC, macrophage, and B cell." (PMID 37894300, 2023). "Transfected PCa cells were injected subcutaneously into nude mice, and the results showed that YY1 overexpression stimulated the growth of subcutaneous tumours." (PMID 37771187, 2023). "This work proposed a drug-development strategy that combined the regulation of YY1-mediated tumor progression with ICIs for the treatment of HCC." (PMID 37408047, 2023). "Previous studies have proven that many clinical drugs targeting YY1 have sound therapeutic effects on YY1-mediated tumor drug resistance or malignant progression." (PMID 37081988, 2023). "Knocking down YY1 using RNA interference has also demonstrated efficacy in inhibiting tumor growth and sensitizing tumor cells to chemotherapy." (PMID 37444616, 2023). "We collected the xenograft tumours and performed IHC and immunofluorescence (IF) assays to further identify the role of YY1 in vivo." (PMID 37771187, 2023). "YY1 promotes tumor progression by regulating the expression of genes involved in cell proliferation and survival." (PMID 37444616, 2023). "In preclinical studies, YY1 knockdown promotes apoptosis, inhibits cell proliferation, and enhances the effectiveness of chemotherapy in tumor cells." (PMID 37444616, 2023). "A number of studies have suggested that YY1 is also closely related to the remodeling of tumor immune microenvironment, and PD-L1 expression is regulated by YY1-mediated signal crosstalk." (PMID 37408047, 2023). "The high expression of YY1 is in favor of antioxidant effects in normal nerve cells, despite the fact that it is strongly expressed in a variety of cancers and necessary for tumor formation." (PMID 36837850, 2023). "IHC results showed that USP7 and YY1 expression levels were higher in tumor tissues than in normal liver tissues." (PMID 37408047, 2023).